STAT3 (signal transducer and activator of transcription 3)
Diseases named in the same sentence as STAT3 in open-access papers (continued):
Sharing a sentence is not in itself a finding about the gene and the disease.
tumor (continued). "Tumor-associated macrophages, major components of tumor microenvironment associated with cancer metastasis, induce EMT for colorectal cancer migration and circulating tumor cell-mediated metastasis via JAK2/STAT3/miR-506-3p/FoxQ1 axis activated by IL-6." (PMID 34660694, 2021). "STAT3 is the family member of signal transduction and transcriptional activators (STAT) proteins, which regulate the gene expression related to cell survival and immune response associated with tumor progression and malignancy." (PMID 33957948, 2021). "IL-6 via IL-6R/STAT3 pathway regulates DNMT1 expression in tumor cells." (PMID 33604794, 2021). "In conclusion, PLCG2 may affect IL-6/JAK/STAT3 signaling pathway to form anti-tumor TME, which may depend on the subtype of STS and the role of STAT3 in TME." (PMID 33725976, 2021). "Indeed, the IL-1β secreted in the tumor microenvironment induces the secretion of IL-17 through its effect on CD4 T cells, by driving the differentiation and expansion of Th17 cells, which promote angiogenesis and tumor growth via the STAT3 signaling pathway." (PMID 33498483, 2021). "Like NF-κB, STAT3 is often constitutively activated in malignant tumour cells and immune cells." (PMID 32414156, 2020). "Altogether, this study elegantly demonstrates the dual role of STAT3 in tumor formation." (PMID 32365499, 2020). "It has been shown that phosphorylation of STAT3 can increase cell-cell contact, and thus, STAT3 may be an essential gene for the migration and invasiveness of tumor cells." (PMID 33330321, 2020). "It is suggested that STAT3 could serve as a potential target to impair tumor progression or recurrence." (PMID 33390934, 2020). "Furthermore, Vimentin and N‐cadherin, which function as EMT markers, were regulated by the α5‐nAChR/Stat3/Jab1 axis and contributed to tumour invasion and migration." (PMID 31930655, 2020). "STAT3 is involved in the tumorigenesis process by inducing the transcription of several genes that regulate survival, resistance to apoptosis, metastasis, and angiogenesis in tumor cells." (PMID 33003453, 2020). "Our previous study has disclosed the tumor facilitator role of STAT3 in HB via the ceRNA pattern." (PMID 32493490, 2020). "Furthermore, our group previously reported that CD5 in tumor infiltrating B cells binds to IL-6, and through gp130 induces STAT3 activation to promote cancer development." (PMID 33335857, 2020). "Thus, JAK/STAT3 pathway was activated in control group xenograft tumours but attenuated in siIGF2BP3 xenografts." (PMID 33094561, 2020). "Interestingly, STAT3-mediated Nanog expression can regulate self-renewal and tumor initiation in CD24+ LCSCs." (PMID 33117795, 2020). "Similarly, in GBM preclinical models, momelotinib in combination with temozolomide inhibited STAT3 activation, decreased cell growth, increased apoptosis, and inhibited tumor growth compared to temozolomide monotherapy." (PMID 33521321, 2020). "Meanwhile, these tumor-derived factors that also happen to be STAT3 activators could be transited to the TME, and thus enhance STAT3 signaling in various immune cell subsets and CAFs." (PMID 32972405, 2020). "Since then, various reports substantiated STAT3′s engagement in promoting cancer hallmarks, such as tumor cell proliferation, evasion of apoptosis and angiogenesis by controlling the expression of pro-tumorigenic genes like Cyclin D1/2, c-MYC, MCL1, Survivin, BCL-XL, HGF, HIF-1α and VEGF." (PMID 32365499, 2020). "Our results showed that p-STAT3 might serve as an essential biomarker for tumor invasion and metastasis in ESCC." (PMID 32194797, 2020). "In a healthy condition, IL-22 cannot initiate tumor formation by itself and maintains barrier integrity against cancer development; but under inflammatory conditions, IL-22 directly promotes tumor growth or induces “stemness-like” cancer cells via STAT3-dependent signaling." (PMID 32670290, 2020).
tumor (continued). "Furthermore, STAT proteins have critical roles in the innate immune response (STAT1 and STAT2) and in tumour initiation and progression (STAT3 and STAT5)." (PMID 32899142, 2020). "Inhibition of STAT3 blocked autophagy and reduced tumor growth in mouse xenograft models." (PMID 31963765, 2020). "Among these, the STAT3 signaling pathway is a proinflammatory pathway and may be triggered by the tumor cells." (PMID 33344655, 2020). "STAT3 is involved not only in macrophage differentiation but also in tumor cell proliferation." (PMID 32256354, 2020). "IHC results showed that the protein level of E‐cadherin increased, whereas protein levels of p‐STAT3 (Tyr705), N‐cadherin, and vimentin decreased in the tumor tissues grown from HeLa cells in the RES pretreatment and treatment groups, compared to those in the respective control groups." (PMID 33040485, 2020). "STAT3 inhibitor treatment significantly decreased tumor growth." (PMID 33330068, 2020). "Moreover, targeting the STAT3 gene in myeloid cells resulted in a reduction of Tregs and an increase in tumor-infiltrated CD8+ T cells, which led to effective antitumor immune responses." (PMID 32503584, 2020). "STAT3 activity suppression induces the apoptosis of tumor cells." (PMID 33040485, 2020). "First, in addition to inhibiting levels of STAT3, there may be other mechanisms of the inhibiting effects of astaxanthin on tumor cells." (PMID 32784629, 2020). "Here, Notch family members could lead to IL-6/STAT3 activation, and in other cases the IL-6/STAT3 pathway has given rise to Notch activation, eventually promoting a diversity of tumor-promoting processes in BC cells." (PMID 32605277, 2020). "Most PCa metastases were positive for p-STAT3 staining and STAT3 inhibitor galiellalactone effectively decreased metastatic tumor spread in a mouse model of PCa15, indicating that STAT3 activation may be a crucial promotor in PCa invasion and metastasis." (PMID 32546700, 2020). "Interestingly, both ex vivo and in vivo experimental results indicated that CPAP overexpression promotes tumor growth, metastasis, and angiogenesis by enhancing STAT3 transcriptional activity via direct interactions." (PMID 31511651, 2020). "Sorafenib has the ability to inhibit tumor development by reducing STAT3 phosphorylation." (PMID 33379302, 2020). "This was confirmed by a ~50% reduction of the tumor invasion index in the STAT3 depleted cells." (PMID 32967361, 2020). "Furthermore, Trichomicin exerted antitumor effects by targeting Stat3, NF-κB, and PD-L1 in tumor and stromal cells (Graphical Abstract)." (PMID 32317968, 2020). "Tumor cells have been found to display a high level of IL-22 receptor expression as well as increased IL-22 production by surrounding tumor infiltrating T cells, indicating that IL-22 promotes tumor proliferation by engaging the STAT3 signaling in tumor tissues." (PMID 32670290, 2020). "Overactive STAT3 then promotes the expression of genes involved in proliferation, anti-apoptosis, metastasis, and inflammation, which collectively contribute to malignant transformation and tumor progression." (PMID 31980595, 2020). "In addition, STAT3 regulates a large number of genes involved in immune response and tumor immune surveillance." (PMID 33003453, 2020). "Although studies have extensively examined the molecular pathways involved in the STAT3 regulation in GC, and how anti-tumor compounds can be beneficial in suppressing STAT3 in GC therapy, there are a number of drawbacks that should be considered in further studies." (PMID 32545648, 2020). "Having identified STAT3 as a direct target of miR-769-5p, we next assessed the possibility that STAT3 downregulation may be responsible for the tumor-suppressive roles of miR-769-5p in RB cells." (PMID 32369777, 2020). "Previous studies have demonstrated that STAT3 is overexpressed in many types of tumor cells." (PMID 33390934, 2020).
tumor (continued). "Taken together, we demonstrated that the tumor suppressor SH2D4A is linking STAT3 nuclear and mitochondrial functions, and inhibition of PHB-binding may have therapeutic effects in tumor cells with STAT3 activation." (PMID 33257655, 2020). "Furthermore, we represent how anti-tumor drugs can target STAT3 in suppressing GC progression and metastasis." (PMID 32545648, 2020). "In conclusion, increased phosphorylation of STAT3 in tumour‐conditioned microglia upregulates the expression of IL‐10 and IL‐6 in an mTOR‐dependent fashion with a concomitant reduction in expression of IL‐12 mediated by reduced phosphorylation and nuclear translocation of NF‐κB." (PMID 32567735, 2020). "Thus, both studies not only illustrate the importance of STAT3-NF-κB-CXCL1 signaling for K-RAS-driven lung tumorigenesis, but also demonstrate that tumor intrinsic STAT3 activation can inhibit the formation of a pro-tumorigenic TME." (PMID 32365499, 2020). "In addition, one of the main functions of the activation of the S1PR1 signaling pathway is the continuous activation of STAT3 in the form of phosphorylation, leading to overexpression of NF-κB and IL-6, which promotes tumor development." (PMID 33101013, 2020). "Given the similarities between tumorigenesis and STAT3-dependent immunity, new therapeutic strategies that target STAT3 signaling pathway may open up new avenues for long-lasting and multilayered tumor control." (PMID 32972405, 2020). "Taking everything into account, studies are in agreement with the fact that anti-tumor compounds are able to inhibit STAT3 in different stages, including targeting upstream mediators, the activation of endogenous inhibitors, the downregulation of downstream targets and suppressing STAT3 expression." (PMID 32545648, 2020). "Further work is required to evaluate whether CD103+ cDC1s utilize similar or distinct STAT3 anti-inflammatory or anti-tumor mechanisms in response to TLR3 agonist stimulation." (PMID 31947933, 2020). "Indeed, CDDO-Me has also been shown to target cyclin D1, EGFR, and STAT3 signaling in PyMT tumor cells." (PMID 32300202, 2020). "Pro-inflammatory cytokines contribute to the upregulation of ROS scavengers in CSC and also to downstream STAT3 signaling activation promoting survival of tumor cells, facilitating tumor regrowth, and leading to the development of highly invasive CSC phenotypes." (PMID 32660072, 2020). "The combination of GC7 and cisplatin reversed the upregulation of p-STAT3, c-Myc, and cisplatin-promoted mesenchymal–epithelial transition and, further, contributed in significant tumor volume reduction without distinct body weight loss in animal model." (PMID 32605067, 2020). "Consequently, the decrease of GM-CSF/TSLP muted STAT3/β-catenin signaling and inhibited tumor progression." (PMID 32887217, 2020). "The JAK2/STAT3 signaling pathway has been widely studied in different steps of tumor development and may act as a promising molecular therapeutic target." (PMID 32358527, 2020). "Hence, treating cancer by targeting STAT3 via inhibition of the activation or expression of the molecule, to block the signal transmission pathways of the tumor cells, seems an optimal approach." (PMID 32784629, 2020). "Moreover, atorvastatin treatment decreased tumor growth and weight in an HCC xenograft animal model, which were associated with decreased IL-6 and TERT expression and STAT3 phosphorylation and increased β-gal expression and SA-β-gal activity in tumors." (PMID 32257389, 2020). "Collectively, these results suggest that p-STAT3 might serve as essential biomarker for tumor invasion and metastasis in ESCC." (PMID 32194797, 2020). "IL-6 activation induces JAK/STAT3 pathway in both tumor cells and tumor-infiltrating immune cells." (PMID 33080912, 2020). "Altogether, data from these studies indicate that STAT3‘s function extends far beyond the tumor cell and that blockade of STAT3 signaling might be a promising option to treat NSCLC patients." (PMID 32365499, 2020).
tumor (continued). "Inhibition of STAT3 is reported to sensitize tumour cells to cisplatin-induced apoptosis." (PMID 32661236, 2020). "In vivo, STAT3 and p-STAT3 were also negatively regulated by miR-337-3p in 4T1 tumor models." (PMID 32934214, 2020). "In addition, activation of STAT1 and STAT3 has an opposite effect on tumor survival and growth by regulating a plethora of effector proteins." (PMID 31957537, 2020). "Various studies have shown Bazedoxifene could inhibit tumor growth by targeting the IL-6/GP130/STAT3 signaling pathway." (PMID 32362823, 2020). "IL-32 inhibits tumor growth via inhibition of NF-κB and STAT3 signals in colon and prostate cancer." (PMID 32308549, 2020). "Accordingly, to further promote clinical translation, we tested the hypothesis that UTMC-mediated delivery of STAT3 decoy to human HNSCC would inhibit tumor growth." (PMID 33206698, 2020). "Such interactions could allow tGLI1 to serve as an oncogenic signaling hub similar to STAT3 that permits convergence of several signaling pathways to create a novel mechanism of tumor progression." (PMID 32957513, 2020). "Remarkably, sequential intravenous injections of siRNA against STAT3 induced profound silencing of STAT3 expression in tumor tissue, which resulted in significant downregulation of PD-L1, leading to significant inhibition of tumor growth through inhibition of tumor immune checkpoint." (PMID 32059541, 2020). "Moreover, activation of Jak/STAT3 signaling pathway has been shown to regulate MMP-9 expression in tumor invasion and metastasis." (PMID 33228717, 2020). "It would suggest that tumor cells and stromal cells interdependently regulate IL-6 expression in cancers, which may account for the localized activation of the IL-6/STAT3 pathway." (PMID 33322216, 2020). "Additionally, STAT3 activation promotes the accumulation of tumour regulatory T-cell (Tregs) and blocks the generation of anti-tumour immune responses, which give an adverse effect to the body." (PMID 32863742, 2020). "In this study, Stat3’s overactivation and overexpression in tumour tissues of EOC patients were observed, and we speculated that the persistent stimulation made by the Stat3 signalling pathway is likely to be vital to EOC prognosis." (PMID 31778258, 2020). "KD of p66Shc could obviously inhibit the development and progression of HCC in vitro and in vivo through modulating Signal Transducer And Activator Of Transcription 3 (STAT3) signaling pathway-mediated regulation of tumor microenvironment." (PMID 33203836, 2020). "Furthermore, PP VII suppresses malignance of tumor cells by restraining the immunosuppressive macrophage transformation, which is also managed by STING, via the prevention of activated-STAT3 propagating between macrophages and tumor cells." (PMID 33288772, 2020). "Moreover, in the tumor microenvironment, STAT3 activation in TAMs can lead to inhibition of IL-12 through NFκB pathway blockade." (PMID 33036138, 2020). "Although in physiological conditions neutrophils and macrophages are essential for the elimination of necrotic cells and wound repair, excess of these cells favors tumor development through activation of the IL‐6/Stat3 signaling pathway, which promotes cellular proliferation." (PMID 33326125, 2020). "In addition, curcumin in combination with EGCG reduced the tumor CM-induced transition of normal endothelial cells toward tumor endothelial cells through inhibiting JAK/STAT3 signaling pathway." (PMID 32660101, 2020). "Furthermore, nanocurcumin downregulates PI3K/Akt and JAK/STAT3 signaling pathways, which at least in part have a role in preventing further tumor proliferation and growth." (PMID 33536913, 2020). "Recent studies also verified the important role of STAT3 in tumor microenvironment." (PMID 32733808, 2020). "Subsequently, STAT3 acetylation activates Cyclin D1 promoter and induces the tumor proliferation." (PMID 33382817, 2020).
tumor (continued). "JAK-mediated STAT3 tyrosine phosphorylation not only drives malignant cell proliferation, survival, and invasiveness, but also strongly compromises antitumor immunity in the tumor microenvironment." (PMID 33322216, 2020). "The crucial role of STAT3 in facilitating tumor cell growth and survival has been well-established." (PMID 31949487, 2020). "STAT3 excessive activation may be triggered by elevated levels of IL-6 present in the serum or released within the tumor microenvironment." (PMID 32150944, 2020). "In addition, neutrophil-derived reactive oxygen species further decrease the adhesion-promoting properties of the extracellular matrix and inhibit tumor cell apoptosis through activation of NF-kB and STAT3." (PMID 32716955, 2020). "CD8+ T cells were also found accumulated in tumor sites of STAT3−/− mice." (PMID 32503584, 2020). "Notably, tumor cell-intrinsic STAT3 drives the expression of pro-tumorigenic cytokines (e.g., IL-6) and growth factors (e.g., VEGF), thus enhancing the recruitment of tumor-promoting myeloid cells such as TAMs or MDSCs to the TME." (PMID 32365499, 2020). "STAT3 inhibitor has been widely studied in the field of anti-tumor treatment." (PMID 32071300, 2020). "Previous studies also found that STAT3 contributes to chemo-resistance of various tumor types." (PMID 32733808, 2020). "Furthermore, it increases the expression of some tumor-relevant proteins, such as integrin β1 and Bcl-3 (B-cell lymphoma-3) and the activities of others, such as STAT3 and AKT." (PMID 33228022, 2020). "Likewise, ample evidence suggests that STAT3 regulates many aspects of tumor angiogenesis at the transcriptional level." (PMID 33335857, 2020). "MiR-9600 by targeting STAT3 could suppress tumor progression, induce cell cycle arrest at G1/S phase, and promote paclitaxel sensitivity in NSCLC." (PMID 33330110, 2020). "The upregulation of the S1pr1 gene can activate STAT3 and promote tumour growth and metastasis." (PMID 31957271, 2020). "STAT3 pathway plays an important role in the development of tumor cells." (PMID 33330466, 2020). "The down-regulation of the mitochondrial complexes (I-IV) and inhibition of signal transducer and activator of transcription 3 (STAT3) were also observed in in vivo study of a tumor xenograft derived from athymic nude mice which exhibited greater anti-tumor effect compared to curcumin." (PMID 32825505, 2020). "In addition to controlling the number of CSCs, TAM can also increase the tumor‐initiating capacity of CSCs through STAT3 signaling pathway." (PMID 32885589, 2020). "Notably, Hsp90 is important for the functional competence of STAT3 which governs the tumor microenvironment and cancer progression." (PMID 33390934, 2020). "Persistent STAT3 activation promotes tumor progression and metastasis in various cancer." (PMID 32963220, 2020). "STAT3 is also a crucial tenet of tumor-induced Tregs biology." (PMID 33584695, 2020). "Thus, we evaluated AR‐42's effects on phospho‐STAT3 (pSTAT3) in gastrocnemius muscle from C‐26 tumor‐bearing animals." (PMID 31930715, 2020). "Our data suggest these treatments may improve the ability of human non-lymphoid organ cDC1s to induce anti-tumor immunity and underscore the importance of evaluating tumor immune responses in STAT3 inhibitor clinical trials." (PMID 31947933, 2020). "STAT3 plays a very crucial role in the initiation and progression of cancer by promoting a pro-carcinogenic inflammatory microenvironment, while suppressing anti-tumor immunity." (PMID 32824207, 2020). "However, the efficacy of specific inhibitors regulating STAT3 varies among tumor types because the percentage of activated STAT3 is individualized in cancer cells." (PMID 32486001, 2020). "However, as is the case for other NFkB- and IFN-signaling pathway inhibitors, these pathway inhibitors also exhibit favorable effects, as for example indicated by the fact that STAT3 also elicits tumor-suppressive functions." (PMID 32630675, 2020).